MIR770 (microRNA 770)
Synonyms: hsa-mir-770; MIRN770
Gene: MicroRNA gene on chromosome 14 (100,852,390 to 100,852,487, forward strand). Ensembl gene ENSG00000211574.
Gene Ontology:
Biological process: miRNA-mediated post-transcriptional gene silencing
Cellular component: RISC complex
Homologues: Orthologues: chimpanzee ptr-mir-770 (100% identical), macaque mml-mir-770 (100% identical), mouse Mir770 (77% identical), rat Mir770 (77% identical).
Diseases named in the same sentence as MIR770 in open-access papers:
MIR770 is named in the same sentence as 2 diseases in open-access papers, as found by Europe PMC text mining. Sharing a sentence is not in itself a finding about the gene and the disease. The quoted sentences say what the papers report.
diabetic nephropathy (1 paper, 2024). "Studies have shown that an increase in Mir770 expression leads to worsening diabetic nephropathy via apoptosis, while reducing Mir770 expression results in decreased apoptosis in glioma cell lines." (PMID 39497124, 2024).
MIR770 also shares sentences with these, for which no sentence is quoted: glioma (1 paper).